MTOR (mechanistic target of rapamycin kinase)
Diseases named in the same sentence as MTOR in open-access papers (continued):
Sharing a sentence is not in itself a finding about the gene and the disease.
hyperlipidemia (continued). "In summary, Rg1 improves renal function in DN rats by inhibiting hyperlipidemia-induced pyroptosis in podocytes via targeting mTOR/NF-κB/NLRP3 signaling." (PMID 33133213, 2020). "The proportions of adverse events in LAM patients were quantified, and the common toxicity events during the mTOR inhibitors therapy were oral mucositis, hyperlipidemia, headache, bone marrow suppression, diarrhea and cough." (PMID 30107845, 2018). "However, the evidence that everolimus, still caused hyperlipidemia in LDL receptor-null mice suggest that a decrease in LDL-receptor expression is unlikely to be the only factor that contributes to hyperlipidemic effects seen in patients treated with mTOR inhibitors." (PMID 25885920, 2015). "PI3K/AKT/mTOR inhibition exacerbates hyperlipidemia via impaired lipid clearance." (PMID 40699849, 2025). "In T2D patients, mTOR dysregulation will promote hyperlipidemia, inflammation and vasoconstriction." (PMID 39200267, 2024). "We speculate that fatty acids in the maternal circulation, such as OA, regulate placental functions critical for fetal growth by interaction with mTOR and that late pregnancy hyperlipidemia may be critical for increasing nutrient transfer to the fetus." (PMID 38223199, 2024). "Alisma targeting the FKBP38/mTOR/SREBPs pathway improves hyperlipidaemia." (PMID 38098069, 2023). "The use of mTOR inhibitors in humans resulted in hyperlipidemia." (PMID 37896137, 2023). "Therefore, there is an urgent need to develop a combination strategy to overcome mTOR inhibitors-induced hyperlipidemia during tumor treatment." (PMID 37896137, 2023). "It was reported that inhibition of PCSK9 could be an effective method for reducing the unfavorable side effects of mTOR inhibitors-induced hyperlipidemia." (PMID 37896137, 2023). "There are few reported cases of AIH patients unresponsive to standard drugs treated with mTOR inhibitors, with variable results; the side effects include hyperlipidemia, mouth ulcerations, legs ulcers, thrombocytopenia, proteinuria, rash, and decreased resistance to infection." (PMID 34580437, 2022). "Hyperlipidemia is a common side effect in patients undergoing treatments that inhibit mTOR." (PMID 35986566, 2022). "Taking together, in hyperlipidemia status, the IL-35–promoted ApoE–/– CCR5+ Tregs exhibit a lower Akt/mTOR activation, suggesting that IL-35 may play a vital role in maintaining a stable Treg immunosuppressive signature in hyperlipidemia." (PMID 34622804, 2021). "Furthermore, the inhibitory effects of Rg1 on the activation of NLRP3 were reversed by LEU, which strongly suggested that Rg1 decreased hyperlipidemia-induced pyroptosis in podocytes by inhibiting the mTOR/NF-κB/NLRP3 axis." (PMID 33133213, 2020). "While mTOR inhibitors (e.g., sirolimus) and AMPK activators (e.g., metformin) have shown promise in clinical trials for SLE and RA, their effects are often accompanied by off-target consequences, such as hyperlipidemia and infection risk, highlighting the need for more selective targeting." (PMID 41476956, 2025). "Consequently, co-delivery of PCSK9 and mTOR inhibitors may provide a promising strategy for avoiding tumor chemotherapy-induced hyperlipidemia, but such a combination is rarely reported." (PMID 37896137, 2023). "By regulating the PI3K/AKT/mTOR signaling pathway, BBR‐CA decreases the expression of SREBP‐1, reduces de novo lipid synthesis and thus treats hyperlipidemia." (PMID 40928061, 2026). "There is some evidence that pre-treatment lipid values can predict the presence, but not necessarily the severity, of hyperlipidemia associated with mTOR-inhibitor therapy, which suggests that individual factors (genetic, co-morbid, or otherwise) may contribute to the risk of severe increases." (PMID 38094495, 2023).
hyperlipidemia (continued). "Hyperlipidemia is frequently observed in patients treated with VEGFR (vascular endothelial growth factor receptor)–TKIs, as well as mTOR inhibitors (such as rapamycin, temsirolimus and everolimus)." (PMID 37612751, 2023). "Moreover, it can affect the expression of SREBP‐1 in the nucleus through the PI3K/AKT/mTOR pathway, and consequently influence the expression of downstream lipogenesis genes such as SCD1 and ACC, thus achieving the purpose of treating hyperlipidemia." (PMID 40928061, 2026). "Therefore, in recent years, many studies have focused on the PI3K/AKT/mTOR/SREBP‐1 signaling pathway and attempted to identify inhibitors of the PI3K/AKT/mTOR/SREBP‐1 signaling pathway to control the occurrence and development of hyperlipidemia." (PMID 40928061, 2026). "Despite optimal therapy for dyslipidaemia, many patients (up to 50%) with hyperlipidaemia after mTOR inhibitors therapy do not achieve the cholesterol and triglyceride concentrations recommended by the most prestigious scientific societies." (PMID 36009482, 2022). "In addition, Rg1 also inhibited hyperlipidemia-induced NLRP3 inflammasome in the podocytes, which was abrogated by the mTOR activator L-leucine (LEU)." (PMID 33133213, 2020). "Pediatric patients that received mTOR inhibitor therapy were more likely to experience mouth ulceration, stomatitis, convulsion, acneiform rash, arthralgias, diarrhea, thrombocytopenia, hyperlipidemia and lipoproteinemia than those treated with non-mTOR inhibitor therapy." (PMID 25574245, 2015). "Taken together, our results suggest that BBR‐CA could function by modulating the PI3K/AKT/mTOR signaling pathway, resulting in decreased nuclear expression of SREBP‐1, as well as reduced expression of stearoyl‐CoA desaturase 1 and acetyl‐CoA carboxylase, thus alleviating hyperlipidemia." (PMID 40928061, 2026).
schizophrenia (69 papers, 2012 to 2025). A major psychotic disorder characterized by abnormalities in the perception or expression of reality. "An overexpression or increased functionality of the Akt/mTOR signaling pathway predisposes individuals to schizophrenia." (PMID 38365306, 2024). "Overall, this indicates that disrupted mTOR signaling impairs neurodevelopment and ultimately leads to an increased risk of schizophrenia." (PMID 38365306, 2024). "The significance of mTOR in neuron development and its regulation of translational control and protein synthesis implicated that mTOR is involved in the pathology of schizophrenia." (PMID 36835497, 2023). "The Akt/GSK3β/mTOR signaling pathway has a consistent multifaceted association with the pathophysiology of schizophrenia." (PMID 35757972, 2022). "Dysfunctional mTOR signaling increases the prediction of neurological disorders associated with AD, abnormal morphology of the nervous system and schizophrenia." (PMID 35450293, 2022). "Existence of variants of the AKT1 gene in patients with schizophrenia supports the idea of the key role played by impaired Akt-mTOR signaling in the pathogenesis of this psychiatric disorder." (PMID 36430976, 2022). "Overstimulation of the mTOR system in specific brain areas has been linked with cognitive deficits seen in schizophrenia." (PMID 34366935, 2021). "Both environmental factors and extracellular stimuli previously implicated in the development of schizophrenia are known to control the mTOR cascade." (PMID 32265715, 2020). "In line with this, a number of genetic studies linked mTOR-related genetic alterations to schizophrenia." (PMID 30061532, 2018). "Functional schizophrenia-associated DPYSL2 variant affects mTOR signaling and has an impact on cellular phenotypes." (PMID 27801893, 2016). "Our results suggest that reduced transcription and mTOR-regulated translation of certain DPYSL2 isoforms increase the risk for schizophrenia." (PMID 25416705, 2014). "Both DPYSL2 and mTOR are associated with common physiological functions such as neuronal polarity, axonal outgrowth and synaptic strength as well as brain disorders including schizophrenia." (PMID 37144098, 2023). "Studies have found that abnormal expression of the PI3K-Akt-mTOR signaling pathway is associated with the pathogenesis of schizophrenia, and inhibitors of this pathway may have therapeutic effects." (PMID 37816766, 2023). "The mTOR signaling pathway is associated with schizophrenia pathogenesis as well as with extrapyramidal adverse reactions to antipsychotic drugs, which also may be mediated by impaired mTOR-dependent autophagy." (PMID 36430976, 2022). "The regulation of risk genes of schizophrenia on neurodevelopment might be accomplished by convergence in the AKT/mTOR pathway." (PMID 34630179, 2021). "Remarkably, a growing evidence shows that mTOR dysfunction may underlie a variety of psychiatric syndromes, including mood disorders, drug addiction, and schizophrenia." (PMID 30061532, 2018). "Remarkably, the identification of rare genetic variants of ULK1 in a cohort of schizophrenic patients by means of exome sequence analysis strengthens the idea of a key role of both disrupted mTOR signaling and autophagy in the pathophysiology and susceptibility to schizophrenia." (PMID 30061532, 2018). "Disrupted mTOR signaling cause impaired function of protein synthesis in schizophrenia." (PMID 28117656, 2016). "We then questioned whether all three biological pathways concerned with translational control—eIF2, mTOR and eIF4 signaling—were implicated in schizophrenia genomics data." (PMID 26485547, 2015). "Furthermore, defects in PI3K-Akt-mTOR signaling underlie some forms of intellectual disability and autism and may contribute to schizophrenia." (PMID 30618607, 2018). "A comprehensive study of the contribution of dysfunction AKT/mTOR signaling to the pathogenesis of schizophrenia is needed." (PMID 41283305, 2025).
schizophrenia (continued). "Analyses of post-mortem brain tissues from individuals with schizophrenia have shown reduced expression and reduced phosphorylation of ribosomal protein S6, a downstream effector of mTOR, thus indicating a potential pathway hypofunction." (PMID 40650013, 2025). "The aim of the study is to determine the expression of the protein kinase AKT/mTOR signaling pathway in peripheral mononuclear cells (PMCs) of patients with schizophrenia." (PMID 41283305, 2025). "There is substantial evidence demonstrating abnormalities in the PI3K/AKT/mTOR expression and activity in different animal schizophrenia models and postmortem probes of patients." (PMID 41283305, 2025). "The aim of the study is to investigate the expression of the main protein kinases of the AKT/mTOR signaling pathway in the peripheral mononuclear cells of patients with schizophrenia." (PMID 41283305, 2025). "A dysfunction in the activity of the mTOR signaling pathway during neurodevelopment caused by social and environmental factors may alter dendritic spine morphology, leading to the impairment of synaptic plasticity and neurogenesis and thereby increasing the risk of developing schizophrenia." (PMID 38365306, 2024). "Chadha and Meador-Woodruff further showed a reduction in AKT-mTOR expression or mTOR phosphorylation in dorsolateral prefrontal cortex tissues in postmortem brain samples of people with schizophrenia." (PMID 38365306, 2024). "Previously, the focal adhesion‐PI3K‐Akt–mTOR‐signaling pathways were regarded as potential comorbidity mechanisms shared by schizophrenia (SZ), bipolar disorder (BD), and MDD." (PMID 38358062, 2024). "Pathways analysis on the 203 placental-specific schizophrenia TWAS genes supported the enrichment for mTOR signaling, insulin, estrogen, and EIF2 signaling." (PMID 37188697, 2023). "In particular, the gene expression changes associated with schizophrenia risk in placenta indicated EIF2 signaling pathways, inhibition of mTOR signaling, activation of the Estrogen Receptor, and Insulin secretion and receptor signaling." (PMID 37188697, 2023). "Apart from being enriched in mTOR and EIF2 signaling in both sexes, the schizophrenia risk genes are also associated with an alteration of insulin signaling in females and with inflammatory signaling in males." (PMID 37188697, 2023). "PACAP can activate AMPK function, and PACAP is proved to mediate the mTOR pathway via PAC-1 receptor activation in model of schizophrenia." (PMID 37891608, 2023). "DISC1 encodes disrupted in schizophrenia 1, which is involved in neurogenesis and astrogenesis, and is a positive regulator of WNT signaling and negative regulator of PI3K/AKT/mTOR signaling." (PMID 35440587, 2022). "This study highlights the role of the NRG1/ERbB4 and PI3K/AKT/mTOR signaling pathways in the neuroprotective effects of aripiprazole and sertindole on ketamine-induced schizophrenia in rats." (PMID 35876932, 2022). "In a schizophrenia model, the administration of 60 mg/kg of ketamine twice a day for 7 days decreased mTOR expression in the prefrontal cortex and hippocampus." (PMID 35677378, 2022). "Accordingly, recent independent studies support the notion of mTOR hypofunction in schizophrenia patients." (PMID 35757972, 2022). "This study investigates the effects of aripiprazole and sertindole on the NRG1/ErbB4 and PI3K/AKT/mTOR signaling pathways in ketamine-induced schizophrenia in rats." (PMID 35876932, 2022). "Oxidative stress can also interact with the mTOR pathway resulting in the development of cognitive symptoms within schizophrenia." (PMID 34366935, 2021). "To date, relatively few studies have examined the relationship between the expression levels of the mTOR pathway and the pathogenesis of schizophrenia." (PMID 34348681, 2021).
schizophrenia (continued). "Our results revealed significantly lower MTOR mRNA expression levels in patients with acute schizophrenia before treatment than in healthy controls, and the levels did not change significantly after olanzapine treatment." (PMID 34348681, 2021). "This study aimed to examine the expression of mTOR pathway genes in patients with schizophrenia treated with olanzapine, which is considered an mTOR inhibitor and autophagy inducer." (PMID 34348681, 2021). "A gene expression microarray analysis of patients with first-episode schizophrenia before and after treatment with risperidone or paliperidone showed that the mTOR pathway was involved in extrapyramidal system reactions." (PMID 34348681, 2021). "Signal pathways of 3-phosphatidylinositol kinase, inositol phosphatase (PI3K/PTEN/AKT/mTOR), protein kinase or mitogen activated kinases (MAPK/ERK) mediated by mTOR can be a mechanism explaining the formation of cardiometabolic complications of schizophrenia." (PMID 32121669, 2020). "The main goal of this study was to evaluate the status of mTOR signaling pathway in postmortem prefrontal cortex (PFC) samples of subjects with schizophrenia." (PMID 32265715, 2020). "The mechanistic target of rapamycin (mTOR), also known as mammalian target of rapamycin, represents a critical integrator of neuronal activity and synaptic inputs that plays a role in schizophrenia and other neuropsychiatric diseases." (PMID 32265715, 2020). "This review addresses the role of mTOR-dependent autophagy dysfunction in a variety of neuropsychiatric disorders, to focus mainly on psychiatric syndromes including schizophrenia and drug addiction." (PMID 30061532, 2018). "Here, we wish to point out that the detrimental effects of METH on both DA neurotransmission and mTOR-dependent cell clearing systems produce behavioral alterations that are reminiscent of schizophrenia." (PMID 30061532, 2018). "Our results support the functional importance of the DPYSL2 DNR and a role for mTOR signaling in schizophrenia." (PMID 27801893, 2016). "We previously reported a schizophrenia-associated polymorphic CT di-nucleotide repeat (DNR) at the 5′-untranslated repeat (UTR) of DPYSL2, which responds to mammalian target of Rapamycin (mTOR) signaling with allelic differences in reporter assays." (PMID 27801893, 2016). "In two different developmental rat models of schizophrenia specifically neonatal phencyclidine and postweaning isolation, the mammalian target of rapamycin (mTOR) pathway was found to be persistently upregulated in the prefrontal cortex." (PMID 23801939, 2013). "In conclusion, the present observations demonstrate that 5-HT6 receptors recruit and activate mTOR to compromise cognition both in pharmacological paradigms and in developmental models of schizophrenia." (PMID 23027611, 2012). "We can speculate that PI3K/AKT/mTOR signaling may play a significant role in the pathogenesis of schizophrenia." (PMID 41283305, 2025). "Similarly, mTOR-related signaling appears dysregulated in schizophrenia, further supporting its role as a shared therapeutic target." (PMID 40650013, 2025). "A combination of genetic and environmental factors, such as the disruption to the mTOR signaling pathway and prenatal stress, are hypothesized to lead to the development of schizophrenia." (PMID 39149410, 2024). "Therefore, in this review, we discuss the functional roles of the mTOR signaling cascade in the pathogenesis of schizophrenia and provide a theoretical foundation for the development of novel therapeutic targets based on mTOR signaling." (PMID 38365306, 2024). "Taken together, these data suggest that deregulation of the mTor-DPYSL2 molecular pathway may be involved in NDDs such as schizophrenia or ID." (PMID 37144098, 2023). "Thus, this study aimed to investigate the effects of aripiprazole and sertindole on the NRG1/ERbB4 and PI3K/AKT/mTOR signaling pathways in ketamine-induced schizophrenia in rats." (PMID 35876932, 2022).